DNMT1 (DNA methyltransferase 1)
Diseases named in the same sentence as DNMT1 in open-access papers (continued):
Sharing a sentence is not in itself a finding about the gene and the disease.
acute promyelocytic leukemia (7 papers, 2012 to 2025). An aggressive form of acute myeloid leukemia (AML), characterized by arrest of leukocyte differentiation at the promyelocyte stage, due to a specific chromosomal translocation t(15;17) in myeloid cells. "Our previous study using acute promyelocytic leukemia cells uncovered its effect on the downregulation of DNA methyltransferase 1 (DNMT1) which is often overexpressed in cancer cells resulting in the repression of tumor suppressors via hypermethylation." (PMID 27525019, 2016). "Our previous study had showed that THL could intensively decrease the protein level of DNA methyltransferases 1 (DNMT1), an important enzyme for the aberrantly DNA methylation, in acute promyelocytic leukemia cells." (PMID 23097677, 2012). "Di Croce found that PML-RAR fusion protein, an oncogenic transcription factor, recruited DNMT1 and DNMT3A to retinoic acid receptor beta 2 leading to its methylation and subsequent gene silencing in acute promyelocytic leukemia (APL)." (PMID 38696033, 2024).
Burkitt lymphoma (7 papers, 2014 to 2025). A rare form of malignant mature B-cell non-Hodgkin lymphoma. "Here, we report that in T-ALL and Burkitt’s lymphoma MYC directly caused the overexpression of both DNMT1 and DNMT3B." (PMID 29100357, 2017). "Further examination of the underlying regulatory mechanism in T-ALL and Burkitt’s lymphoma revealed a direct correlation of DNMT1 and DNMT3B expression with high MYC levels, which led us to assess whether transcriptional regulation is MYC-dependent." (PMID 29100357, 2017). "It remains to be seen whether DNMT1 or DNMT3B overexpression is also associated with poor clinical outcome in T-ALL and Burkitt’s lymphoma." (PMID 29100357, 2017). "By utilizing a tetracycline-regulated MYC transgene in a mouse T-ALL (EμSRα-tTA;tet-o-MYC) and human Burkitt’s lymphoma (P493-6) model, we demonstrated that DNMT1 and DNMT3B expression depend on high MYC levels, and that their transcription decreased upon MYC-inactivation." (PMID 29100357, 2017). "Approximately 85% of Burkitt lymphoma (BL) patients display DNMT3B overexpression, which contributes to DNA methylation in conjunction with DNMT1." (PMID 40299416, 2025). "Subsequent ChIP analysis revealed that MYC occupies sites within the DNMT1 and DNMT3B regulatory regions, suggesting a direct transcriptional regulation in mouse T-ALL and human Burkitt’s lymphoma-like cells." (PMID 29100357, 2017). "Taken together, clinical specimens resembled our data from mouse and human cell line models in regard to DNMT1 and DNMT3B overexpression in T-ALL and Burkitt’s lymphoma." (PMID 29100357, 2017). "Taken together, DNMT1 and DNMT3B expression exhibited a correlation to MYC levels in both mouse T-ALL and human Burkitt’s lymphoma models." (PMID 29100357, 2017). "We identified canonical E-box sequences in close proximity to the MYC enrichment peak near the transcription start site (TSS) of DNMT1 and DNMT3B in both T-ALL, and Burkitt’s lymphoma-like cells." (PMID 29100357, 2017). "In summary, the genomic location analysis together with expression profiling indicates that MYC directly binds to DNMT1 and DNMT3B in T-ALL and Burkitt’s lymphoma, thereby establishing both DNMTs as direct transcriptional targets of the MYC oncoprotein." (PMID 29100357, 2017). "Based on our expression profiling, we conclude that DNMT1 and DNMT3B are consistently overexpressed in MYC-driven T-ALL and Burkitt’s lymphoma cell lines, while DNMT3A is overexpressed in human T-ALL cell lines only." (PMID 29100357, 2017). "To ascertain that DNA methylation was affected by Iso-3, consistently with inhibition of DNMT1 activity, we investigated expression levels of the aryl hydrocarbon receptor (AHR) gene in Burkitt's lymphoma RAJI cells." (PMID 27006469, 2016). "Furthermore, DNA methylation-mediated repression of LMP1 expression in EBV-superinfected Burkitt lymphoma cell lines in vitro is initiated by the DNMT3B de novo methyltransferase and maintained by the DNMT1/UHRF1 maintenance methylation complex." (PMID 38620028, 2024). "Similarly, DNMT1 mRNA expression was increased in all human T-ALL and Burkitt’s lymphoma cell lines (17.30- to 41.54-fold, P<0.001) compared to normal spleen and B-cells, respectively." (PMID 29100357, 2017). "To determine whether DNMT1 and DNMT3B transcription in T-ALL and Burkitt’s lymphoma-like cells is directly regulated by oncogenic MYC, we performed chromatin immunoprecipitation (ChIP) analysis measuring MYC binding to the genomic loci of DNMT1, DNMT3A and DNMT3B." (PMID 29100357, 2017). "Overexpression of DNMT1 and DNMT3B has been observed in Burkitt lymphoma (BL) tumour samples, independent of Epstein–Barr virus (EBV) status." (PMID 41297313, 2025). "To unravel the role of DNA methyltransferases (DNMTs) in MYC-driven hematopoietic malignancies, we performed expression profiling for DNMT1, DNMT3A and DNMT3B comparing MYC-driven T-ALL and Burkitt’s lymphoma cells to non-malignant control cells." (PMID 29100357, 2017).
cerebellar ataxia (7 papers, 2017 to 2025). A neurological syndrome characterized by clumsy and uncoordinated movement of the limbs, trunk, and cranial muscles. "Here we report a novel DNMT1 mutation in a sporadic case of a Chinese patient with cerebellar ataxia, multiple motor and sensory neuropathy, hearing loss and psychiatric manifestations." (PMID 30342480, 2018). "ADCA type 1 refers to cerebellar ataxia accompanied by a range of additional features, encompassing conditions like SCA1-4, 8, 10, 12-14, 15, 17-22, 25, 27, 28, 31, 32, 34-37, 38, 42-44, 46, and 47, as well as DNMT1-related ataxia and DRPLA." (PMID 39958116, 2025).
diabetic nephropathy (7 papers, 2021 to 2024). "Parthenolide has shown potential as a DNA methylation inhibitor—it was observed to inhibit DNA methyltransferase 1 (DNMT1), a noteworthy effect considering DNMT1 was found to be upregulated in diabetic nephropathy mice and high glucose-induced MPC5 cells." (PMID 38318147, 2024). "The diagnostic value of peripheral blood α1-MG, DNMT1 relative expression and VEGF level in diabetic nephropathy." (PMID 37861555, 2023). "Gondaliya et al26 found that miR29b might effectively target DNMT3B, DNMT1 and DNMT3A contributing in the development of diabetic nephropathy in renal proximal tubular cells." (PMID 33484504, 2021). "Although, we found no investigation pointing to the role of DNMT1 in the IgAN pathogenesis, inhibition of this epigenetic factor in the kidneys of diabetic nephropathy db/db mice model led to podocyte protective effects." (PMID 34861820, 2021).
diffuse large B-cell lymphoma (7 papers, 2015 to 2025). "Loo and his colleagues’ work suggest the involvement of DNMT1 in the activation of cell cycle and DNA replication in diffuse large B-cell lymphoma cells." (PMID 29759079, 2018). "Notably, AID facilitates TET2-mediated demethylation of the FANCA gene as a transcriptional cofactor in diffuse large B-cell lymphoma (DLBCL), while paradoxically collaborating with DNMT1 to maintain methylation at the BCL6 promoter." (PMID 40270606, 2025). "Overexpression of DNMT1 was observed in other hematologic malignancies, including T-cell acute lymphoblastic leukemia (ALL), T-cell lymphomas, and diffuse large B-cell lymphoma (DLBCL)." (PMID 36614080, 2022).
hereditary sensory and autonomic neuropathy type 1E (7 papers, 2014 to 2025). "Autosomal dominant cerebellar ataxia, deafness, and narcolepsy (ADCADN) and hereditary sensory neuropathy type IE (HSN1E) are both caused by heterozygous mutation in the DNMT1 gene." (PMID 25750614, 2014).
idiopathic pulmonary fibrosis (7 papers, 2014 to 2024). Idiopathic pulmonary fibrosis (IPF) is a nonneoplastic pulmonary disease that is characterized by the formation of scar tissue within the lungs in the absence of any known cause. "The expression of miR-17–92 was decreased in patients with idiopathic pulmonary fibrosis (IPF), while the expression of DNMT1 increased." (PMID 35478963, 2022).
myeloid malignancies (7 papers, 2017 to 2021). "For example, patients suffering from myeloid malignancies displayed effective silencing of DNMT1 in response to initial decitabine/azacytidine treatments; however, these levels rebounded during patient relapse." (PMID 34358067, 2021). "We identified upregulation of Dnmt1 as a consequence of BCR-ABLp210, and we show that HSPC-restricted expression of Dnmt1 in transgenic mice is sufficient to phenocopy the BCR-ABLp210-associated DNA methylation changes and induce myeloid malignancies." (PMID 29955131, 2019). "DNMT1-depletion terminates malignant self-replication but maintains normal hematopoietic stem cell self-replication —a vital therapeutic index when treating myeloid malignancies, since normal hematopoiesis is needed to reverse low blood counts, the cause of morbidity and death." (PMID 32770088, 2021). "Together, these data show that HSPC-restricted expression of Dnmt1 is sufficient to phenocopy the DNA hypomethylation phenotype induced by BCR-ABLp210 expression in the same compartment and to promote the development of myeloid malignancies." (PMID 29955131, 2019).
osteoporosis (7 papers, 2022 to 2025). A condition of reduced bone mass, with decreased cortical thickness and a decrease in the number and size of the trabeculae of cancellous bone (but normal chemical composition), resulting in increased fracture incidence. "This study provides additional insights into the molecular mechanisms of the lncRNA SNHG1/PTBPT1/DNMT1/Opg pathway in the pathogenesis of osteoporosis and presents novel ideas for developing new prevention and treatment measures for osteoporosis." (PMID 34854215, 2022). "For instance, in a rat model of disuse osteoporosis, local injection of siRNA targeting DNMT1 (a gene-silencing form of DNMTi) effectively improved compromised femoral microstructure, offering direct evidence for the bone-protective effects of DNMT1 inhibition." (PMID 41282636, 2025). "Thus, an in-depth investigation of the effect of targeted DNMT1 inhibition on the treatment of osteoporosis is warranted in light of our findings." (PMID 35238333, 2022). "In the present study, we show that DNMT1 protein expression is reduced during OB differentiation, while enhanced in osteoprogenitors and chondroblasts of trabecular bone from human and mice with senile osteoporosis (SOP)." (PMID 35238333, 2022). "Importantly, the current study revealed a novel role of DNMT1 in control of chondrocyte and OB differentiation of MSC and consequent skeletal development, implicating a potential role of DNMT1 in the development of osteoporosis." (PMID 35238333, 2022). "Likewise, an elevated DNMT1 protein level was also observed in osteoprogenitors lining the trabeculae surface in bone sections from the femoral trochanter of osteoporosis patients, in comparison with that of a healthy young male." (PMID 35238333, 2022). "Therefore, we hypothesized that lncRNA SNHG1 could regulate the expression of DNMT1 and subsequently influence Opg methylation status, contributing to the occurrence of osteoporosis, but it needs further determination." (PMID 34854215, 2022). "In a post‐transcriptional regulation manner, lncRNA SNHG1 upregulated DNA methyltransferase 1 (DNMT1) expression, resulting in osteoprotegerin (OPG) hypermethylation and decreased OPG expression, in turn contributing to osteoporosis." (PMID 38318762, 2024). "In the pathogenesis of osteoporosis, high levels of lncRNA SNHG1 increased the expression of DNMT1 via interacting with PTBP1." (PMID 38057885, 2023). "In summary, lncRNA SNHG1 upregulated the expression of DNMT1 via interacting with PTBP1, resulting in Opg hypermethylation and decreased Opg expression, which in turn enhanced BMSC adipogenic differentiation and contributed to osteoporosis." (PMID 34854215, 2022). "In sum, our study demonstrated that lncRNA SNHG1 upregulated the expression of DNMT1 via interacting with PTBP1, resulting in Opg hypermethylation and decreased Opg expression, which in turn enhanced BMSC adipogenic differentiation and contributed to osteoporosis." (PMID 34854215, 2022).
renal carcinoma (7 papers, 2014 to 2024). A carcinoma arising from the epithelium of the renal parenchyma or the renal pelvis. "Bik was overexpressed in several cancerous cell lines such as lung, prostate, and renal carcinoma when treated with DNA methyltransferase 1 inhibitor and histone deacetylase inhibitor." (PMID 37736508, 2023). "Interestingly, another DNMT1 inhibitor, 5‐aza‐2′‐deoxycytidine, failed to induce vacuolization in renal cancer cells and did not exhibit significant synergistic effects with everolimus." (PMID 39119834, 2024). "Our results showed that UHRF1 gene expression was correlated with four methyltransferases (DNMT1, DNMT2, DNMT3A, and DNMT3B) in a variety of tumors, and KICH KIRC KIRP was positively correlated with methyltransferase, suggesting that UHRF1 may be an epigenetic driver of renal cancer type." (PMID 35656341, 2022).
rheumatoid arthritis (7 papers, 2020 to 2025). A chronic, systemic autoimmune disorder characterized by inflammation in the synovial membranes and articular surfaces. "Nakano and colleagues measured the protein levels of DNMT1 and DNMT3A in fibroblast-like synoviocytes (FLS) from rheumatoid arthritis (RA) and OA patients." (PMID 32140068, 2020). "DNMT1 could downregulate PTEN, while PTEN overexpression reduced inflammation and activated fibroblast-like synoviocytes via AKT signaling in rheumatoid arthritis." (PMID 35765066, 2022). "Furthermore, rheumatoid arthritis (RA) patients treated with methotrexate (MTX), which reduces the level of DNMT1, were characterized by restored Tregs functions and higher Foxp3 expression caused by a decrease in upstream enhancer methylation." (PMID 34281195, 2021).
thyroid cancer (7 papers, 2013 to 2025). "Therefore, inhibiting the expression of DNMT1 is a potential therapy for thyroid cancer." (PMID 32751889, 2020).
amyotrophic lateral sclerosis (6 papers, 2018 to 2025). Amyotrophic lateral sclerosis (ALS) is a neurodegenerative disease characterized by progressive muscular paralysis reflecting degeneration of motor neurons in the primary motor cortex, corticospinal tracts, brainstem and spinal cord. "Highly expressed DNMT1 and DNMT3A were detected in the spinal cord and skeletal muscle of mice with amyotrophic lateral sclerosis; however, treatment with the DNMT inhibitor RG108 improved motor function and prolonged survival in the affected mice." (PMID 38584203, 2024).
Cerebral ischemia (6 papers, 2018 to 2025). Restriction of arterial blood supply to the brain associated with insufficient oxygenation to support the metabolic requirements of the tissue. "According to data published previously DNMT1 expression and subsequent global DNA methylation that suppresses protein biosynthesis increased at 16–24 h after cerebral ischemia and reperfusion." (PMID 34830365, 2021). "Additionally, decitabine may have ameliorated cerebral ischemia by inhibiting the complexes formed by DNMT1 with other proteins." (PMID 40356977, 2025). "Therefore, we investigated changes in the levels of DNMT1, DNMT3a, and DNMT3b, in addition to measuring DNA methylation, in the brain after severe cerebral ischemia and examined the effects of DNMT inhibitors on excitotoxic injury in cultured neuronal cell to define a therapeutic target." (PMID 33177984, 2020). "The current data showed the elevation of DNMT1 and HDAC3 in cerebral ischemia corresponding with the changes in the previous studies." (PMID 39281061, 2022). "Although reducing DNMT1 levels can protect mice from the effects of cerebral ischemia, the absence of DNMT1 does not prevent ischemic brain injury." (PMID 40356977, 2025).
colitis (6 papers, 2018 to 2025). Inflammation of the colon. "Additionally, ELF4 suppression mediated by DNA methyltransferase 1 (DNMT1) methylation of its promoter drives the transformation of ulcerative colitis to colitis-associated cancer." (PMID 40083328, 2025). "Results indicated that alpinetin (15, 30 mg/kg) significantly inhibited expression of DNMT-1 in colons of colitis mice." (PMID 30166541, 2018). "Then, effects of alpinetin and TCDD on DNMT-1 level in colons of colitis mice and CD4+ T cells were examined." (PMID 30166541, 2018). "Alpinetin (30 mg/kg) up-regulated expression of miR-302, downregulated expression of DNMT-1, and promoted association of CREB and promoter region of Foxp3 in colons of colitis mice." (PMID 30166541, 2018). "In conclusion, alpinetin ameliorated colitis in mice via activating AhR, regulating miR-302/DNMT-1/CREB signals, therefore promoting Treg differentiation." (PMID 30166541, 2018). "Finally, CH223191 abolished the amelioration of alpinetin on colitis, induction of Treg cells and regulation of miR-302/DNMT-1/CREB signals in colons of colitis mice." (PMID 30166541, 2018). "Furthermore, alpinetin significantly promoted expression of miR-302 but not others, and restrained expression of DNMT-1 and methylation level of Foxp3 promoter region in CD4+ T cells and colons of colitis mice." (PMID 30166541, 2018).
colon adenocarcinoma (6 papers, 2012 to 2024). "Since we previously reported, reelin downregulation in human colon adenocarcinoma together with upregulation of both DNMT-1 and ApoER2, we next examined how these genes behave in each type of colon lesion." (PMID 36290310, 2022). "These reelin changes were the opposite of those in DNMT-1 expression and activity, which, via the hypomethylation of the reelin promoter in acute colitis and hypermethylation in colon adenocarcinoma, increases or represses reelin expression, respectively." (PMID 36290310, 2022).
COVID-19 (6 papers, 2020 to 2025). A disease caused by infection with severe acute respiratory syndrome coronavirus 2. "DNMT1 and DNMT3A had an inverse correlation with the severity of COVID-19 (r = -0.242 and -0.233, respectively)." (PMID 36840831, 2023). "DNMT1, DNMT3A, and DNMT3B were inversely correlated with COVID-19 (r = -0.215, -0.528, and -0.335, respectively)." (PMID 36840831, 2023). "In this study, we analyzed the expression profile of DNMTs (DNMT1, DNMT3A, DNMT3B) and HDACs (HDAC2 and HDAC3) in COVID-19 patients." (PMID 36840831, 2023). "In our study, all DNMTs were inversely correlated with COVID-19 disease, whereas DNMT1 and DNMT3A, but not DNMT3B, had an inverse relationship with disease severity." (PMID 36840831, 2023). "DNMT1 and DNMT3A were negatively correlated with COVID-19 severity." (PMID 36840831, 2023). "In contrast to previous reports, DNMT3A and DNMT3B expression was found to be significantly downregulated in COVID-19 cases, whereas DNMT1, HDAC2, and HDAC3 expression did not change." (PMID 36840831, 2023). "To conclude, DNMT1, HMGA1, and HMGA2 might be central TFs in the TF–gene regulatory network in COVID-19/NSCLC." (PMID 35721149, 2022). "We conducted a case-control study to investigate the differential expression of DNMT1, DNMT3A, DNMT3B, HDAC2, and HDAC3 in the blood of 120 patients (30 mild, 30 moderate, 30 severe, and 30 critical) and 30 healthy subjects without COVID-19." (PMID 36840831, 2023).